MTHFD2 (methylenetetrahydrofolate dehydrogenase (NADP+ dependent) 2, methenyltetrahydrofolate cyclohydrolase)
Diseases named in the same sentence as MTHFD2 in open-access papers (continued):
Sharing a sentence is not in itself a finding about the gene and the disease.
cancer (continued). "MTHFD2 has been reported to be overexpressed in several malignant tumors and is implicated in cancer development." (PMID 34231329, 2021). "The importance of MTHFD2 in cancers is manifested by its upregulated expression in tumor cells and the association with cancer patients outcome." (PMID 32411609, 2020). "Taken together, our data demonstrated that MTHFD2 is significantly associated with LCa and mediates in cancer growth and proliferation, stemness, cellular metabolic reprogramming-dependent tumor aggressiveness, oxygen sensing and oxidative stress response." (PMID 32759461, 2020). "This review aims to highlight the potential functions of MTHFD2 in cancers, particularly focusing on its diagnostic/prognostic value and the effects of its knockdown on aggressive phenotypes." (PMID 32411609, 2020). "The overexpression of both MTHFD1L and MTHFD2 has been reported in cancer cells where it is associated with greater mortality." (PMID 31147722, 2019). "Database analysis revealed that cancer cells carrying the resistance mutation in EGFR or MET amplification appear to depend on MTHFD2 for growth." (PMID 30532069, 2019). "First, we examined MTHFD2 expression in patients with different cancers and analyzed the association between the cancer prognosis and expression of MTHFD2 to validate the possibility of MTHFD2 as a drug discovery target." (PMID 30582043, 2018). "MTHFD2, another gene associated with one carbon metabolism, is considered to be an important player for various types of cancer and correlated with mitochondrial folate metabolism." (PMID 29312619, 2017). "MTHFD2 is integral to mitochondrial one-carbon metabolism, a metabolic system recently implicated in rapid cancer cell proliferation." (PMID 28210221, 2017). "MTHFD2 knockdown in HCT116 cells was associated with reduced cancer cell proliferation and marked cell death, consistent with the effect that we have previously observed after Wig-1 knockdown in these cells." (PMID 26672765, 2016). "For example, MTHFD2 is a mitochondrial enzyme fundamental in one-carbon metabolism, a metabolic system recently implicated in rapid cancer cell proliferation." (PMID 26672765, 2016). "For example, the ability of miR‐9 to inhibit cell proliferation has been linked to downregulation of MTHFD2 expression in cancer cells or TLX/NR2E1 in neural stem cells." (PMID 26416703, 2015). "Methylenetetrahydrofolate dehydrogenase 2(MTHFD2) has been widely reported as a potential and promising anti-cancer target, but its role and underlying mechanisms remain unclear in MM." (PMID 40280919, 2025). "SHMT2 and MTHFD2, encoding two key enzymes of the mitochondrial arm of the one-carbon pathway, have been reported to be among the most consistently upregulated metabolic genes in cancer." (PMID 40698729, 2025). "MTHFD2 deficiency reduces disease severity in inflammatory models, suggesting its potential as a therapeutic target for autoimmune diseases, though its role in cancer immunity requires careful consideration due to immune cell dependency." (PMID 40734168, 2025). "In addition, MTHFD2 expression is closely associated with mTORC1 signaling, which controls protein, lipid, and nucleotide synthesis in normal and cancer cells." (PMID 38755125, 2024). "Previous studies have shown that tumor microenvironment is associated with the efficacy of immunotherapy and that MTHFD2 might induce cancer immune evasion through PD-L1 upregulation." (PMID 39958609, 2024). "MTHFD2 was first reported in 2015 to be present in the nucleus in both cancer cell lines and human tumors, and to be associated with regions of newly replicated DNA, pointing to a role in driving cancer cell proliferation." (PMID 40604332, 2024). "Moreover, MTHFD2 plays a pivotal role as a prognostic factor in cancer, and MTHFD2 loss accelerates aging-like alterations to promote tumor growth." (PMID 39668825, 2024). "We identified MTHFD2 as both an aging risk factor and a protective factor in aging-related cancer." (PMID 39668825, 2024).
cancer (continued). "In addition to its metabolic functions, MTHFD2 has been implicated in promoting cancer immune evasion." (PMID 39668825, 2024). "In addition, another study has shown that MTHFD2 can upregulate the expression of PD-L1, thereby causing cancer immune evasion." (PMID 38130721, 2023). "Moreover, to explain the role of the MTHFD2 enzyme in causing cancer, gene knockdown studies have been reported that showed the impact of the MTHFD2 enzyme in causing depletion of the cancers." (PMID 37872243, 2023). "MTHFD2 was found to be positively associated with several immunological features of an inflamed tumor microenvironment (TME) in various cancers and could predict BLCA patients’ prognosis." (PMID 38130721, 2023). "In summary, the expression level of MTHFD2 was associated with immunological features in pan-cancers, including BLCA, and could assess the prognosis of patients." (PMID 38130721, 2023). "Therefore, we used TIMER to explore the association between immune infiltration levels and MTHFD2 expression level in various cancer types." (PMID 35135596, 2022). "MTHFD2 expression was remarkably elevated in UCB, suggesting that MTHFD2 could be a promising biomarker for BLCA as well as novel target for anti-cancer immunotherapy since its close association with immune infiltration." (PMID 35581573, 2022). "Furthermore, these studies did not address the requirement for enzymatic activity of MTHFD2, or how loss of MTHFD2 mechanistically contributes to cancer cell death." (PMID 35228749, 2022). "Unregulated MTHFD2 promotes malignant characteristics of cancer cells, but the underlying mechanisms and how it is regulated are still largely unknown." (PMID 35790743, 2022). "We conclude that MTHFD2 could be a promising biomarker for BLCA as well as a novel target for anti-cancer immunotherapy due to its close association with immune infiltration." (PMID 35581573, 2022). "However, as MTHFD2 inhibitors cause cancer-specific replication stress, triggering the ATR-Chk1 signaling cascade, we observed a strong synergy between MTHFD2 inhibitors and ATR and Chk1 inhibitors." (PMID 35228749, 2022). "MTHFD2 overexpression is also linked with a poor clinical outcome in several cancers." (PMID 35693982, 2022). "Dysregulated proliferation is a hallmark of tumorigenicity in cancer cells, and thus, we investigated whether MTHFD2 regulates tumor growth." (PMID 34231329, 2021). "Notably, serine catabolism is elevated in cancer, and the genes encoding MTHFD2 and SHMT2 are among the top five differentially expressed genes in tumors and normal tissues for a wide range of cancers, including EOC." (PMID 35008360, 2021). "But it remains elusive whether the high expression in cancer attributes to the MTHFD2-related genomic mutation or to the induction of other essential oncogenic drivers." (PMID 32411609, 2020). "In sum, MTHFD2 depletion could result in cancer cell death and impair key features associated with cancer progressions, such as proliferation, invasion, migration, and metastasis." (PMID 32411609, 2020). "Since abnormal angiogenesis is an important hallmark in GBM, targeting MTHFD2 may halt the progression of GBM by either slowing cancer cell proliferation or inhibiting abnormal angiogenesis, or both." (PMID 32411609, 2020). "While the cytosolic pathway may independently contribute to nucleotide biosynthesis, our results correlate with the recent demonstration that MTHFD2 expression is commonly elevated in many cancers and associated with poor survival in breast cancer patients." (PMID 25621173, 2015). "A study showed that the expression of metabolic enzymes highlights the key role of MTHFD2 and mitochondrial folate pathway in cancer, MTHFD2 is an integral part of mitochondrial one-carbon metabolism, a metabolic system recently associated with the rapid proliferation of cancer cells." (PMID 39588377, 2024).
cancer (continued). "Moreover, focusing on clinical trials involving elderly cancer patients and studying then age-related expression and function of MTHFD2 can provide insights into its role in slowing down aging-associated cancer progression and improving therapeutic outcomes for this population." (PMID 39668825, 2024). "Another enzyme involved in mitochondrial one-carbon metabolism, methylenetetrahydrofolate dehydrogenase/cyclohydrolase (MTHFD2), may represent a viable therapeutic target in cancer, since the loss of MTHFD2 increases ROS levels and sensitizes cancer cells to oxidant-induced cell death." (PMID 33114695, 2020). "Methylenetetrahydrofolate dehydrogenase 2 (MTHFD2), a central enzyme in one-carbon metabolism, is increasingly recognized for its oncogenic roles in both cancer cells and immune compartments." (PMID 41752156, 2026). "Studies indicate that glucose-6-phosphate dehydrogenase (G6PD), along with malic enzymes and methylenetetrahydrofolate dehydrogenase 2 (MTHFD2), represents the most pertinent enzymes examined through IHC concerning cancer aggressiveness." (PMID 41710542, 2026). "An alternative approach towards targeting the MTHFD2 activity in cancer cells was inadvertently highlighted through the discovery of the TH9619 drug." (PMID 41303507, 2025). "The expression pattern of MTHFD2 and the detrimental effects of its targeting on cancer cells offered a strong rationale and motivation for the development of inhibitors against this enzyme." (PMID 41303507, 2025). "MTHFD2 overexpression boosts folate cycle activity in the mitochondria, generating the formate overflow that fuels the nucleotide synthesis needs of cancer cells." (PMID 39847116, 2025). "This review provides a retrospective on four decades of advancements on MTHFD2 that have revealed its key roles in the folate pathway, amino acid and redox homeostasis, and the metabolism of cancer and immune cells." (PMID 41303507, 2025). "Of the two, MTHFD2 is one of the most highly upregulated genes in cancer, including breast cancer and colorectal cancer." (PMID 39847116, 2025). "Would it then be preferable to specifically target MTHFD2, which is strongly expressed in cancer cells, while sparing the MTHFD2L isozyme?" (PMID 41303507, 2025). "In the case of cancer, MTHFD2 holds potential, particularly for precision medicine, combination therapies, and biomarker development." (PMID 41303507, 2025). "For example, genomic deletion of MTHFD2 in cancer cell lines appears to have been more tolerated than transient inhibitions using RNAi or chemical inhibitors." (PMID 41303507, 2025). "There is then great potential for MTHFD2 as an immune target, building upon inhibitors already under development as anti-cancer molecules." (PMID 41303507, 2025). "As MTHFD2, which is overexpressed in cancers, promotes growth and metastasis, targeting MTHFD2 by its inhibitor TH9619 shows potent activity in inhibiting AML xenograft growth in vivo." (PMID 40734168, 2025). "Clearly delineating the extent and conditions whereby the cytosolic pathway is unable to compensate for targeting of MTHFD2 is an urgent subject with direct impact on the anti-cancer potential of targeting this enzyme." (PMID 41303507, 2025). "Firstly, the investigation into the mechanism by which knocking down MTHFD2 followed by formate supplementation impacts cancer progression is an area that requires further exploration." (PMID 40756341, 2025). "Collectively, this paper painted the picture of MTHFD2 as a highly appealing novel cancer target, apparently being both required and restricted to transformed cells of several cancer types." (PMID 41303507, 2025). "The first question is why cancer cells ultimately upregulate MTHFD2, and how it contributes to the growth and survival of cancer cells." (PMID 41303507, 2025). "A potentially important link between higher MTHFD2 expression and cancer was already suggested by the earliest work on this enzyme." (PMID 41303507, 2025).
cancer (continued). "How is MTHFD2 expression regulated in cancer cells, and is it needed to drive their enhanced growth?" (PMID 41303507, 2025). "MTHFD2L is thus likely a housekeeping gene allowing a baseline of mitochondrial 1C folate flux, with isozyme switching to MTHFD2 occurring in many cancers." (PMID 41303507, 2025). "A number of issues and strategies, however, still need to be addressed and clarified for targeting MTHFD2 in cancer." (PMID 41303507, 2025). "Folic acid metabolism enzyme methylenetetrahydrofolate dehydrogenase 2 (MTHFD2) activity is correlated with cell proliferation rates in several cancers." (PMID 40219043, 2025). "Some studies propose that the development of cancer can reactivate embryogenesis-specific enzymes, such as MTHFD2, for which levels have been shown to drop significantly after birth." (PMID 40219043, 2025). "A previous study on different tumors observed higher MTHFD2 profile in 25 out of 31 types of cancer (80.6%), including the ccRCC subtype." (PMID 38422037, 2024). "In ovarian cancer cells, MTHFD2 promoted cancer cell progression by activating the signal transducer and activator of transcription 3 (STAT3) pathway, which has been implicated in cancer cell proliferation and metastasis." (PMID 40604332, 2024). "The overexpression of MTHFD2 not only supports cancer cell migration and invasion but also indicates poor clinical outcomes." (PMID 38794278, 2024). "Further research in this area is needed to explore the possibility of combining MTHFD2 inhibition with dietary interventions to improve cancer cell death." (PMID 40604332, 2024). "In this study, we show that the MTHFD2 protein modulates homologous recombination (HR) repair of DNA double‐strand breaks (DSBs) in human cancer cells." (PMID 38533616, 2024). "In this context, it has become evident that MTHFD2 plays a key role as a significant regulator in the mitochondrial folate pathway in cancer cell metabolism." (PMID 38422037, 2024). "Although the age-related implications of MTHFD2 alterations in the genesis and prognosis of cancer remain to be fully clarified, MTHFD2 has emerged as a promising target for therapeutic interventions." (PMID 39668825, 2024). "The recognition of MTHFD2’s pervasive presence and multifaceted roles across a spectrum of cancers underscores the quest for targeted interventions tailored to combat its influence." (PMID 38794278, 2024). "The outcomes of our study provide significant insights into desirable and undesirable structural elements for rational structure-based design of new and selective inhibitors of MTHFD2 against cancer." (PMID 39256448, 2024). "Methylenetetrahydrofolatedehydrogenase/cyclohydrolase 2 (MTHFD2),a pivotal mitochondrial enzyme in one-carbon metabolism, is significantlyupregulated in various cancers but minimally expressed in normal proliferatingcells." (PMID 39591507, 2024). "MTHFD2 is of particular interest, since it has been shown to be expressed only in embryonic tissues but becomes re-activated in cancer tissues." (PMID 38540202, 2024). "Nevertheless, the fact that several MTHFD2 inhibitors that inhibit MTHFD2 catalytic activity have shown promising results in impairing cancer progression in vitro and in vivo supports that MTHFD2 catalytic function is highly relevant for tumorigenesis." (PMID 40604332, 2024). "SHMT2 and MTHFD2, regarded as oncogenes, are significantly upregulated in various cancer types and promote cancer cell survival." (PMID 38279895, 2024). "MTHFD2 has been the subject of exhaustive scrutiny within the domain of cancer research because of its linkage to the metabolic adaptation of tumors." (PMID 39668825, 2024). "MTHFD2 is described as the second (among > 20 000) most overexpressed gene in cancer versus non‐malignant tissue, thus being highly cancer‐specific." (PMID 38533616, 2024). "We found that MTHFD2 localizes to the nucleus of cancer cells to maintain DNA and histone methylation and guarantee proper mitotic progression." (PMID 40604332, 2024).
cancer (continued). "MTHFD2 has become a highly attractive therapeutic target due to its consistent upregulation in cancer tissues and its major contribution to tumor progression, although it also performs vital functions in proliferating healthy cells." (PMID 40604332, 2024). "We observed elevated expression levels of SHMT2 and MTHFD2 genes in cancer cells compared to normal cells (p-values < 0.001)." (PMID 38331894, 2024). "Elevated expression of MTHFD2 is recurrently noted in diverse cancer manifestations due to its overexpression concomitant with heightened cellular proliferation, invasive tendencies, and resistance to chemotherapy." (PMID 39668825, 2024). "Overexpression of MTHFD2 in various types of cancer cells enhancing PD-L1 expression and increasing immune escape of tumor cells was studied." (PMID 38755125, 2024). "To comprehensively describe the expression of MTHFD2 across a spectrum of tissues and its correlation with clinicopathological features in cancer patients, we conducted an exhaustive exploration employing an online database." (PMID 39668825, 2024). "The prognostic role of MTHFD2 in cancer patients requires validation in additional cohorts to confirm its prognostic significance." (PMID 39668825, 2024). "Many studies have demonstrated the contribution of MTHFD2 to various aspects of cancer development, such as prognosis, cell proliferation, tumor growth, migration and invasion, or metastasis, in a wide range of cancer types." (PMID 40604332, 2024). "MTHFD2 can also be induced by interferon-γ via> the AKT-mTORC1 pathway in several cancer types, resulting in the upregulation of programmed death-ligand 1 (PD-L1) and immune evasion." (PMID 40604332, 2024). "MTHFD2, which is pivotal in one-carbon metabolism, is notably upregulated in various cancers, presenting a novel target for radiopharmaceutical application." (PMID 38794278, 2024). "In support of this notion, growing evidence has revealed that MTHFD1 and MTHFD2 levels are notably upregulated and correlated with poor prognosis across various cancer types." (PMID 38723197, 2024). "Although studies have shown that folate metabolism affects the immune microenvironment, such as MTHFD2 promoting basal and IFN‐γ stimulated PD‐L1 expression, one role of MTHFD2 in human cancer development is promoting tumor immune escape." (PMID 39415848, 2024). "Previous studies have shown that the inhibition of MTHFD2 expression suppresses malignant phenotypes in various cancers and that the effects of MTHFD2 depletion vary among different types of cancer cells." (PMID 37480214, 2023). "MTHFD2 expression levels were up-regulated in the majority of cancers and particularly in TNBC, in which higher expression levels indicated a poorer prognosis." (PMID 36726381, 2023). "The high expression of MTHFD2 is also correlated with the shorter survival of several cancers, including breast cancer, colorectal cancer, kidney cancer, and liver cancer, thus becoming a promising prognostic biomarker and therapeutic target." (PMID 38130721, 2023). "To assess the MTHFD2 expression in cancers, we analysed the TIMER database and verified the results using the GEPIA." (PMID 37480214, 2023). "In cancer, the mitochondrial one-carbon branch is upregulated and MTHFD2 is the most differentially expressed gene between cancer and noncancer cells." (PMID 37949226, 2023). "The expression of MTHFD2 was found to be positively correlated with numerous immunoregulators in most cancers, especially in BLCA, CHOL, KIRC, KIRP, LIHC, and THCA." (PMID 38130721, 2023). "MTHFD2 expression levels have been reported to be higher in human embryonic cells, while most normal adult tissues demonstrate low expression, which provided a theoretical basis for reliably targeting MTHFD2 for the treatment of cancer." (PMID 36726381, 2023). "The heatmap demonstrated that MTHFD2 expression was correlated with lots of immune cells’ infiltration in cancers." (PMID 38130721, 2023).